DVL2 (dishevelled segment polarity protein 2)
Diseases named in the same sentence as DVL2 in open-access papers (continued):
Sharing a sentence is not in itself a finding about the gene and the disease.
autosomal dominant Robinow syndrome (1 paper, 2024). Autosomal dominant Robinow syndrome (DRS) is the more common type of Robinow syndrome (RS) characterized by mild to moderate limb shortening and abnormalities of the head, face and external genitalia. "Additionally, the autosomal dominant Robinow syndrome rFzd2p.TRP548*-GFP variant was shown to reduce recruitment of human DVL2-FLAG in HEK293T cells." (PMID 38967226, 2024).
bladder cancer (1 paper, 2024). "The downregulation of Wnt pathway-related proteins such as Wnt5a/b, DVL2, LRP-6, and phosphorylated LRP-6 upon POLR3G knockdown was further confirmed by Western blotting, indicating that POLR3G might influence bladder cancer behavior through the Wnt signaling pathway." (PMID 39039528, 2024). "The downregulation of Wnt pathway-related proteins such as Wnt5a/b, DVL2, LRP-6, and phosphorylated LRP-6 upon POLR3G knockdown was further confirmed by Western blotting, indicating that POLR3G may affect bladder cancer behavior through the Wnt signaling pathway." (PMID 39039528, 2024).
cleft palate (1 paper, 2026). Cleft palate is a fissure type embryopathy that affects the soft and hard palate to varying degrees. "In summary, this study identifies the DVL2 variant that is fixed and breed defining in several breeds as a risk factor for cleft palate in dogs." (PMID 42037250, 2026).
cognitive deficits (1 paper, 2023). "The mammalian orthologs of these genes, especially DVL2 and KCNA1/2, are implicated in epilepsy and episodic ataxia which are associated with both glutamate excitotoxicity and hippocampal based cognitive deficits." (PMID 37351153, 2023).
colon adenocarcinoma (1 paper, 2012). "Our studies have also revealed that β-catenin and Dvl-2 are upregulated along with DACT1, and demonstrate that there is a trend toward poor survival in patients with tumors that have higher scores for DACT1 expression in colon adenocarcinomas." (PMID 22470507, 2012).
congenital heart disease (1 paper, 2020). A heart disease that is present at birth. "Further, the functional variant rs139365823 in pre-miR-138 enhanced the miR-138-mediated inhibitory regulation of DVL2 and conferred the risk for congenital heart disease in a Chinese population." (PMID 31919492, 2020).
dwarfism (1 paper, 2021). "These body proportions will also need to be studied in a larger cohort to confirm whether mesomelic dwarfism is a part of the phenotype in DVL2 homozygous dogs." (PMID 33599851, 2021).
hyperlipidemia (1 paper, 2018). "We found in our previous study that hyperlipidemia reduced osseointegration in rats via suppressing the expression of phosphor-Dvl2 as well as promoting expression of ubiquitinated-Dvl2." (PMID 30386554, 2018). "MiR-29a-3p/Dvl2/Fzd4 may serve as a promising therapeutic target for hyperlipidemia osseointegration." (PMID 30386554, 2018). "Dishevelled 2 (Dvl2) mRNA was declined in peri-implant bone tissue of high-fat (HF) group than normal group, while frizzled 4 (Fzd4) mRNA declined on day 5 and increased from day 10 to day 20 after implantation in hyperlipidemia rats than in normal rats." (PMID 30386554, 2018). "Moreover, we demonstrated that miR-29a-3p enforced osseointegration by targeting Dvl2 and Fzd4 in the Wnt/β-catenin pathway, and this enforcement could be impaired by hyperlipidemia." (PMID 30386554, 2018).
metastatic disease (1 paper, 2023). "Similarly, patients whose tumors had high expression of DVL2 and MAP3K5 were more likely to progress to metastatic disease (log-rank P = 0.017 and P = 0.000083, respectively)." (PMID 37534375, 2023).
muscular dystrophy (1 paper, 2019). Muscular dystrophy (MD) refers to a group of more than 30 genetic diseases characterized by progressive weakness and degeneration of the skeletal muscles that control movement. "Although MyoF has been proven to be the pathogenic gene of muscular dystrophy, its antagonism against autophagy by stabilizing Dvl-2 has not yet been determined." (PMID 31623157, 2019).
myelomeningocele (1 paper, 2020). Myelomeningocele is the most severe form of spina bifida. "Dvl2 is already implicated in the cause of myelomeningocele, because two to three percent of Dvl2 double knockout mice display spina bifida phenotype." (PMID 32970752, 2020). "DVL2, a human homolog of the Dishevelled gene family, associated with myelomeningocele in the EA population." (PMID 32970752, 2020). "As mentioned in the section on PCP, DVL2 associates with myelomeningocele in the EA population." (PMID 32970752, 2020). "Therefore, loss of correct DVL2 function in some EA population subjects may cause myelomeningocele by preventing convergent extension during neural tube closure through disruption of PCP signaling." (PMID 32970752, 2020). "The genes PORCN, DVL2, CDH2, FUZ are already suspected to play a role in NTD development from studies in animal models and in some cases humans, however the remaining thirteen genes reported here are new in their possible association with myelomeningocele." (PMID 32970752, 2020).
neuroblastoma (1 paper, 2016). Neuroblastoma (NB) is the most common solid, extracranial childhood tumor. "To test this hypothesis, we transiently co-transfected neuroblastoma (SH-SY5Y) cells with constructs harboring human DVL1, DVL2 or DVL3 with a FLAG epitope tag in the N-terminus and EGFP in the C-terminus." (PMID 27008544, 2016).
pilocytic astrocytoma (1 paper, 2019). Pilocytic astrocytoma is a rare subtype of low-grade glioma of the central nervous system characterized by a well circumscribed, often cystic, brain tumor with a discrete mural nodule and long, hair-like projections that extend from the neoplastic astrocytes. "The lowest frequencies of DVL1 and DVL2 MSI were observed for pilocytic astrocytomas which are benign tumours and not prone to malignant progression." (PMID 30468298, 2019).
psychosis (1 paper, 2013). "Our results show that lower expression of DVL2 and to a lesser extent higher expression of GSK3B are associated with more severe negative but not positive symptoms in psychosis." (PMID 24236287, 2013).
pulmonary arterial hypertension (1 paper, 2017). Pulmonary arterial hypertension (PAH) is a group of diseases characterized by mean pulmonary artery pressure >20 mmHg and elevated pulmonary arterial resistance leading to right heart failure. "In addition, Dvl-2 was depleted while Daam-1 expression was elevated in IPAH, in contrast with specimens from associated pulmonary arterial hypertension cases and controls." (PMID 28288669, 2017).
rapidly progressive glomerulonephritis (1 paper, 2021). Inflammation of the glomeruli that is characterized by a rapid loss in renal function with glomerular crescent formation observed on biopsy; it is often seen in patients with concomitant autoimmune disease, like Goodpasture's syndrome or systemic lupus erythematosus. "The NTN model mirrors human rapidly progressive glomerulonephritis (RPGN), and recently, transcripts for VANGL1, VANGL2, CELSR2, DVL2, DVL3, PK1, and PK2 were found to be significantly upregulated in two independents cohorts of RPGN biopsies compared to living kidney donor controls." (PMID 33716764, 2021).
rheumatoid arthritis (1 paper, 2017). A chronic, systemic autoimmune disorder characterized by inflammation in the synovial membranes and articular surfaces. "As there is no systematic study to date on Dvl in rheumatoid arthritis (RA), we explored the impact of Dvl2 on proliferation and inflammatory cytokine secretion in RA fibroblast-like synoviocytes (FLSs)." (PMID 28187436, 2017).
schwannomatosis (1 paper, 2022). The least frequent form of the rare genetic disorder neurofibromatosis. "Moreover, reducing maternal genetic interference allowed the detection of an affected homozygous fetus for LZTR1 gene variants causing schwannomatosis disease and wild-type status for the DVL2 gene." (PMID 36406136, 2022).
cancer (36 papers, 2009 to 2025). A tumor composed of atypical neoplastic, often pleomorphic cells that invade other tissues. "Moreover, we observed distinct differences in mRNA expression of cancer associated genes with DVL2 and HER2 inhibition." (PMID 36809986, 2023). "Mechanistically, SETD2 knockdown changes the alternative splicing profile in cancer-associated genes and decreases intron retention in disheveled segment polarity protein 2 (DVL2), resulting in an increase in DVL2 protein, leading to activation of Wnt signaling." (PMID 33923658, 2021). "Hypermethylation of the HADH gene has been identified as one mechanism underlying its downregulation in CRC, where it modulates cancer cell proliferation through the Wnt/β-catenin and Wnt/ROR2/DVL2 signaling pathways." (PMID 41583431, 2025). "Targeting STAT6 effectively reduced DVL2 levels and reduced cancer cell proliferation, emphasizing the key role of DVL2 in CAC progression." (PMID 39594618, 2024). "DVL1 is associated with poor prognosis, DVL2 promotes tumor proliferation and invasion through interaction with PWP1, and DVL3 drives cancer cell invasion and metastasis via Wnt5B-regulated signaling." (PMID 39594618, 2024). "Second, we found that depletion of DVL2 along with HER2 has an additive inhibitory effect on genes involved in cancer invasion." (PMID 36809986, 2023). "First, we observed that DVL2 directly regulates expression of genes involved in cancer hall marks, CCND1, VEGFA and POU5F1." (PMID 36809986, 2023). "The anti-cancer effect of niclosamide was mediated by the downregulation of the Wnt/β-catenin signaling, which downregulated β-catenin, Cyclin D1, DVL2, and p-GSK3β proteins in the ALDH+ treated cells." (PMID 38170015, 2023). "DVL2 is critical in regulating various cellular processes and silencing of DVL2 results in reduced cancer cell proliferation, migration, and invasiveness." (PMID 36809986, 2023). "As a member of an E3 ligase NEDD4 family, NEDD4L not only targets membrane proteins including ion channels and transporters, but also triggers the degradation of certain proteins involved in cancer signaling pathways such as Dvl2, SMAD2, and SMAD7." (PMID 36618071, 2022). "Dvl2 is overexpressed in cancers and is defined as a positive regulator of tumor cell proliferation and motility." (PMID 28187436, 2017). "The E3 ubiquitin (Ub) protein ligase (ITCH) inhibits Wnt/β-catenin signaling in cancers mainly by promoting the ubiquitination and degradation of phosphorylated disheveled 2 (Dvl2)." (PMID 27642589, 2016). "ITCH involved in cancer progression mainly depends on its ability to regulate protein stability and the target proteins including p63, p73, Notch1, Dvl2, RASSF5, and LATS1." (PMID 27642589, 2016). "Examples include members of the MAPK signaling pathway, such as NRAS, a known oncogene; and members of the WNT signaling pathway, DVL2, DVL3, APC and TCF7 which have been previously implicated in colorectal and other cancers." (PMID 19997598, 2009). "Furthermore, when the differential expression results were mapped onto the Kyoto Encyclopedia of Genes and Genomes (KEGG) Pathways in Cancer network, DVL2 and IL8 showed the greatest AA versus CA fold changes." (PMID 37534375, 2023). "Furthermore, BBC3 and DVL2 were involved in Hippo signaling pathways (shown in dark green color box) and cancer pathways (shown in orange color box)." (PMID 35237522, 2022). "Dvl2, as a key mediator of the Wnt pathway, participates in the progression of several cancers." (PMID 35965516, 2022). "In a further study, the WNT signaling antagonist Dapper1 was induced by autophagy-accelerated Dvl2 degradation, which is mediated by GABA(A) receptor–associated protein like 1 (GABARAPL1), a cancer repressor, and p62 is required for the interaction of Dvl2 and GABARAPL1." (PMID 31126310, 2019). "Furthermore, upregulation of dvl2 and dlg2 expression has been found in various forms of cancer as shown in the COSMIC database." (PMID 27536874, 2016).
cancer (continued). "However, some tumors escape this cycle through various factors and our findings suggested that DVL2 might be one of them that aid the cancer cells in suppressing and evading the immune response." (PMID 36809986, 2023). "Reduction in DVL2 function via shRNA resulted in reduced mRNA expression of CCND1 and VEGFA, genes which are involved in cancer cell proliferation and angiogenesis respectively in both SKBR3 and BT474 cells (p < 0.05)." (PMID 36809986, 2023). "We observed an upregulation of CTNNB1 and other genes involved in CTNNB1 stabilization (CSNK2A1, CSNK2B, DVL2, DVL3,) in rHGP cancer areas." (PMID 36691028, 2023). "In contrast to WWOX and DVL2, expression rates of DVL1 and DVL3 were higher in cancer cell lines compared to normal 26-28." (PMID 32368285, 2020). "DVL2 and TGFB1 have repeatedly been shown to act as inductors of epithelial-to-mesenchymal transition (EMT), one of the hallmarks of cancer progression." (PMID 30366472, 2018). "First we approached the established signalling pathways downstream of MCAM: it is known to induce DVL2 and C-JUN phosphorylation in cancer cells and its knockdown leads to the induction of canonical WNT pathway." (PMID 28923978, 2017). "Although METTL16 destabilizes disheveled segment polarity protein 2 (DVL2) mRNA by m6A modification and suppresses its expression, when the expression of DVL2 increases due to decreased METTL16 expression, Wnt/β‐catenin signaling is activated and cancer progression occurs." (PMID 40448344, 2025). "Thus, WWOX suppressor activity relies on its binding capacities to known cancer-related proteins such as p73, deltaNp63, AP2γ, c-jun, Erbb4, c-Met, RUNX2, and Dvl-2." (PMID 30285739, 2018). "Six genes (PDXDC1, ATF7IP2, LIN7C JTB, TTL, DVL2), which regulate the ERG signal transduction pathways, were retained in 4 out of 9 LT patients, were significantly involved in transcriptional mis-regulation in cancer (multiple testing adjusted p-value = 0.025)." (PMID 35773268, 2022). "Importantly, cancer spheroids isolated from group B ascites, i.e. non-activating WNT signaling, showed limited phosphorylation of DVL2 and DVL3 that was not further reduced by LGK974 treatment." (PMID 31903136, 2020).
tumor (35 papers, 2015 to 2025). "The target genes of ITCH (including p63, p73, Dvl2, and Notch1) are closely associated with tumor formation and chemotherapy sensitivity." (PMID 29096676, 2017). "Latterly, ITCH was found to be crucial in the control of proteasome degradation of several important substrates such as p63, p73, Notch1, and Dvl2; all of which are usually associated with tumor formation and chemosensitivity." (PMID 25749389, 2015). "Despite the clear evidence showing the Lgr5‐dependent role in the siRNA assay and the enhanced sensitive to RSPO stimulation in vivo, it is admittedly difficult to dissect whether the enhanced stem cell and tumour phenotypes in the mutant intestine are caused by Lgr5 or Dvl2 or both." (PMID 31867777, 2020). "Due to its ability to enhance immune responses and slow tumor progression, targeting DVL2 offers a dual therapeutic advantage." (PMID 39594618, 2024). "They found that ASPM-iI is predominantly localized in the cytoplasm of tumor cells and interacts with Dvl-2, a member of the Wnt signaling pathway, promoting stemness and aggressiveness." (PMID 39594769, 2024). "The TRIM56-mediated degradation of DVL2 inactivates Wnt signaling and thus inhibits tumor development." (PMID 36902478, 2023). "While previous studies showed correlation of β-catenin with T cell gene expression, little is known about the role of DVL2 in modulating tumor immunity." (PMID 36809986, 2023). "On the contrary, circ-ITCH originates from few exons of ITCH, a ubiquitin-ligase E3, which plays a tumor suppressor by facilitating ubiquitin degradation of DVL2 (Dishevelled segment polarity protein 2) to repress typical Wnt signaling pathway." (PMID 35697671, 2022). "miR-378 family members, especially miR-378a-3p, have been proposed to function as tumor suppressors by suppressing Wnt/β-catenin signaling activation via targeting WNT10a and DVL2." (PMID 34446021, 2021). "While, Dvl-1 protein levels were increased in the nuclei of the tumor tissues, there was a decrease in the nuclear levels of the Dvl-2 and Dvl-3 proteins." (PMID 32368285, 2020). "A study demonstrated that the level of autophagy was inversely correlated with Dishevelled Segment Polarity Protein 2 (Dvl2) expression and activation of Wnt signaling in tumor cells." (PMID 33260729, 2020). "The results of our study demonstrated increased DVL2 expression in all tumour grades when compared with the control tissue." (PMID 30468298, 2019). "Deletion of Dvl2 reduces intestinal length and inhibits neoplasia formation in the APCMin mouse model of CRC." (PMID 29515783, 2018). "Cir-ITCH competitively bound to tumor-associated miRNAs (miR-7, miR-17, and miR-214) to up-regulate the expression of ITCH, promoting the ubiquitination and degradation of phosphorylated Dvl2, and thereby inhibiting the activation of Wnt/β-catenin pathway." (PMID 29096676, 2017). "Although knockdown of Dvl2 (Dvl2-siRNA) is most commonly applied to inhibit the proliferation of tumor cells, we wanted to investigate the effects of overexpressing Dvl2 in RA." (PMID 28187436, 2017). "Given their association with poor prognosis, targeting DVL2 and DVL3 in HCC could offer new therapeutic strategies to inhibit tumor progression and improve patient outcomes." (PMID 39594618, 2024). "DVL2 expression levels are closely correlated with Wnt activity and tumor progression." (PMID 36902478, 2023). "A pilot study in 24 HER2+ BC patients was performed to dissect the role of DVL2 in tumor immunity." (PMID 36809986, 2023). "Additionally, mRNA expression analysis demonstrated that knockdown of DVL2 resulted in upregulation of STAT1, suggesting that DVL2 acts as a negative regulator of tumor suppression." (PMID 36809986, 2023).